SKOR2 (SKI family transcriptional corepressor 2)
Description:
Has transcriptional corepressor activity. In the developing cerebellum, it downregulates BMP signaling resulting in up-regulation of SHH expression in Purkinje cells and promoting their early differentiation. It is also involved in regulating the proliferation of cerebellar granule cell precursors.
Synonyms: Fussel-18; CORL2; FUSSEL18; CH18515; VAFCAS
Tractability: No criterion of Open Targets' tractability assessment is met for any kind of drug.
Gene: Protein-coding gene on chromosome 18 (47,206,169 to 47,251,660, reverse strand). Ensembl gene ENSG00000215474.
Subcellular location: Nucleus; Cytoplasm
Gene Ontology:
Molecular function: sequence-specific double-stranded DNA binding; SMAD binding; DNA-binding transcription factor activity, RNA polymerase II-specific; RNA polymerase II cis-regulatory region sequence-specific DNA binding; chromatin binding; histone deacetylase binding
Biological process: negative regulation of transforming growth factor beta receptor signaling pathway; negative regulation of BMP signaling pathway; negative regulation of transcription by RNA polymerase II; regulation of DNA-templated transcription; negative regulation of transmembrane receptor protein serine/threonine kinase signaling pathway
Cellular component: cytoplasm; nucleus; transcription regulator complex
Genetic constraint (gnomAD): Loss-of-function variants: 40 observed, 42.34 expected, observed/expected ratio (o/e) 0.94, 90% interval 0.73 to 1.23. The synonymous counts are far from expectation, so gnomAD's model fits this gene poorly and the ratio says little. Missense variants: 1,362 observed, 1,034.4 expected, observed/expected ratio (o/e) 1.32, 90% interval 1.26 to 1.38. Synonymous variants: 691 observed, 471.56 expected, observed/expected ratio (o/e) 1.47, 90% interval 1.38 to 1.56.
Homologues: Orthologues: chimpanzee SKOR2 (99% identical), macaque SKOR2 (98% identical), pig SKOR2 (95% identical), dog SKOR2 (94% identical), rat Skor2 (92% identical), mouse Skor2 (92% identical), guinea pig SKOR2 (72% identical), zebrafish skor2 (21% identical). Paralogues in human: SKOR1 (40% identical), SKI (16% identical), SKIL (13% identical).
Diseases named in the same sentence as SKOR2 in open-access papers:
SKOR2 is named in the same sentence as 21 diseases in open-access papers, as found by Europe PMC text mining. Sharing a sentence is not in itself a finding about the gene and the disease. The quoted sentences say what the papers report.
Ataxia (1 paper, 2020). Ataxia refers to impaired coordination of voluntary muscle movement. "This fly transgene data indicates that movement defects in dCORL mutants are most relevant to Fussel18/SKOR2 associated ataxias." (PMID 32161085, 2020). "Thinking broadly, a new hypothesis derived from the preliminary yohimbine data are that treatment of Fussel18/SKOR2 associated ataxia with a norepinephrine antagonist would be therapeutic." (PMID 32161085, 2020).
encephalitis (1 paper, 2023). An acute inflammatory process affecting the brain parenchyma. "SKOR2 IgG-positive patients had subacute or chronic progressive central nervous system involvement, one presenting with encephalitis and seizures (Case 1) and the other with spastic ataxia, dysarthria, dysphagia, cognitive dysfunction, and pseudobulbar affect (Case 2)." (PMID 37795104, 2023).
female infertility (1 paper, 2021). Diminished or absent ability of a female to achieve conception. "Moreover, SKOR2 gene was associated with female infertility in inbred mice." (PMID 33536540, 2021).
gallbladder adenocarcinoma (1 paper, 2023). A carcinoma that arises from glandular epithelial cells of the gall bladder. "SKOR2 IgG represents a novel biomarker for a PNS associated with lung or gallbladder adenocarcinoma." (PMID 37795104, 2023). "Due to the lack of access to gallbladder adenocarcinoma tissue in the second case, we were not able to demonstrate SKOR2 expression in the tumor." (PMID 37795104, 2023).
Hypertension (1 paper, 2022). The presence of chronic increased pressure in the systemic arterial system. "A systematic review of the role of DNA methylation in modifying blood pressure showed that lower methylation levels of SULF1 (sulfate endosulfatase), EHMT2 (Euchromatic Histone Lysine Methyltransferase 2), and SKOR2 (SKI Family Transcriptional Corepressor 2) were associated with hypertension." (PMID 36293177, 2022).
lung adenocarcinoma (1 paper, 2023). A carcinoma that arises from the lung and is characterized by the presence of malignant glandular epithelial cells. "Additionally, we demonstrated the expression of SKOR2 in lung adenocarcinoma tissue, supporting that the SKOR2 autoantigen may be pathogenically associated with the PNS." (PMID 37795104, 2023). "Histopathologic assessment of the lung adenocarcinoma tissue (Case 1) from a single seropositive patient revealed cytoplasmic and nuclear SKOR2 immunoreactivity in the tumor cells." (PMID 37795104, 2023).
paraneoplastic cerebellar degeneration (1 paper, 2023). A rare, immune-mediated disorder characterized by cerebellar degeneration due to the presence of an often undetected malignancy (usually carcinoma or lymphoma) in an anatomic site other than the cerebellum. "SKOR2 autoantibodies may serve as a marker of a cytotoxic T-cell–mediated injury directed through T-cell receptors recognizing SKOR2 peptides, similar to PCA1 or KLHL11 autoantibody-associated paraneoplastic cerebellar degeneration." (PMID 37795104, 2023).
paraneoplastic neurologic syndrome (1 paper, 2023). A paraneoplastic syndrome that involves the nervous system. "Herein, we report the identification of a novel biomarker for paraneoplastic neurologic syndrome (PNS), Sloan-Kettering-Virus-Family-Transcriptional-Corepressor-2 (SKOR2)-IgG, utilizing PhIP-Seq." (PMID 37795104, 2023).
restless legs syndrome (1 paper, 2022). A condition that occurs while resting or lying in bed; it is characterized by an irresistible urgency to move the legs to obtain relief from a strange and uncomfortable sensation in the legs. "Among others Skor1 and Skor2 are involved in the development of Purkinje neurons and a mutation of Skor1 has been found to be associated with restless legs syndrome." (PMID 35030229, 2022).
viral infection (1 paper, 2025). "The augmentation of TGF-β1/SMAD signaling pathway triggered by HIV-2 Vpx, possibly through the downregulation of SKOR2, is indeed a novel finding, which might lead to apoptosis, tissue damage, immunosuppression and the enhancement of viral infection." (PMID 40331967, 2025).
tumor (2 papers, 2023). "According to the literature data, in the physiological state, SKOR2 is present in cells at low levels, but overexpression of this protein is characteristic of tumour cells." (PMID 36675318, 2023). "We report the discovery and validation of autoantibodies against the SKOR2 protein, a novel biomarker for PNS, in two patients with progressive neurological syndromes and an underlying tumor." (PMID 37795104, 2023).
adenocarcinoma (1 paper, 2023). A common cancer characterized by the presence of malignant glandular cells. "SKOR2 IgG represents a novel biomarker for PNS associated with adenocarcinoma." (PMID 37795104, 2023).
cancer (1 paper, 2022). A tumor composed of atypical neoplastic, often pleomorphic cells that invade other tissues. "But neither Skor1 nor Skor2 have been reported to be involved in cancer progression." (PMID 35030229, 2022).
SKOR2 also shares sentences with these, for which no sentence is quoted: Allergy (1 paper); breast carcinoma (1); head and neck squamous cell carcinoma (1); infection (1); intellectual impairment (1); movement disorder (1); ovarian carcinoma (1); spastic ataxia (1).